SRSF1 (serine and arginine rich splicing factor 1)
Diseases named in the same sentence as SRSF1 in open-access papers (continued):
Sharing a sentence is not in itself a finding about the gene and the disease.
breast carcinoma (continued). "Therefore, splicing regulation of Mcl-1 and BIM by SRSF1 may contribute to breast cancer cell survival." (PMID 32106418, 2020). "Additionally, among splicing regulators frequently altered in breast cancers (in >5% of tumors), we found different members of SR protein family (such as SRSF1, SRSF2, SRSF3, SRSF4, SRSF6, SRSF9, SRSF10, SRSF11) with at least one predicted binding motif in the CD44 v10 region." (PMID 33143085, 2020). "Thus, SRSF1 regulates various aspects of breast cancer such as cell proliferation and motility." (PMID 32106418, 2020). "Similarly, SRSF1 expression promotes inclusion of exon 2 of the BH3 domain-containing gene MCL-1 (myeloid cell leukemia-1) giving rise to the antiapoptotic MCL-1L isoform in both breast cancer and choriocarcinoma cells." (PMID 26273603, 2015). "CLK2 knockdown significantly reduced the phosphorylation level of the splicing factor SRSF1, promoted ENAH 11a inclusion, generated ENAH-L isoforms, and facilitated EMT in breast cancer." (PMID 39885614, 2025). "Our findings identified the effects of CYT on identifying the potential regulatory with SRSF1/MYO1B axis via transcriptome analysis and experiment verification, supporting the anti-tumor effects of CYT against drug resistant breast cancer." (PMID 40176901, 2025). "In conclusion, CYT repressed the growth and metastasis of BC cells and recovered drug sensitivity, through SRSF1-regulated the alternative splicing of MYO1B RNAs, which may represent a novel molecular mechanism to overcome drug resistance in breast cancer." (PMID 40176901, 2025). "For instance, circRPAP2 can bind to the oncogenic splicing factor SRSF1 to compete with the binding between SRSF1 and PTK2 pre-mRNA, thereby attenuating SRSF1-mediated alternate splicing of PTK2 and reduce its expression in breast cancer." (PMID 39550559, 2024). "In breast cancer, SRPK1 can mediate SRSF1 phosphorylation and promote angiogenesis by regulating VEGF premRNA splicing to generate proangiogenic isoforms." (PMID 36052258, 2022). "One study found that the SR proteins SRSF1, SRSF2, SRSF3, SRSF5 and SRSF6 are overexpressed in breast cancer." (PMID 36052258, 2022). "To investigate the role of IGF-1 induced SRSF-1 FASN regulation, we knocked down SRSF-1 by RNAi in breast cancer cells and performed RT-qPCR for FASN mRNA expression." (PMID 36096767, 2022). "In our previous study, we demonstrated that Pnn regulates the expression level of SRSF1 and SRSF2 in a breast cancer cell line, MCF-7 (Michigan Cancer Foundation-7), and indicated an SRSF1-dependent Pnn deficiency-induced cellular apoptosis." (PMID 35326115, 2022). "SRSF1 promotes the production of the short isoforms, S6K1 h6A and h6C, which are upregulated in breast cancer and induce the transformation of human mammary epithelial cells." (PMID 33923658, 2021). "More than 30 human splicing factors have now been defined, and some of them are characterized as either proto-oncogenes, such as SRSF1, SRFS3, DAM1, and PELP1, or tumor suppressors, such as RBM and PRMT6, in breast cancer." (PMID 32110852, 2020). "Among these targets, SRSF1 and TRA2B are key splicing activators, both involved in dysregulated splicing in breast cancer." (PMID 30658617, 2019). "Moreover, others have linked more splicing factors such as the hnRNPs, SRSF1, SRPK1, and PTBP1 to breast cancer migration and metastasis formation, making it very interesting to systematically evaluate the role of splicing in breast cancer cell migration in future studies." (PMID 31278301, 2019). "The choice between the long and short isoform is influenced by the splicing factors SRSF1 and SRSF5, which are also frequently upregulated in breast cancer." (PMID 29848666, 2018). "Both genes were found coexpressed in lung and breast carcinomas and MYC depletion downregulates SRSF1 expression in lung cancer cell lines." (PMID 26273603, 2015).
breast carcinoma (continued). "First, in breast tumors and breast cancer cell lines amplification of the SFRS1 gene at chromosomal location 17q23 was detected and the increased DNA copy number correlated with elevated SRSF1 mRNA levels." (PMID 26273603, 2015). "Notably, our data indicate that by targeting SRSF1-mediated alternative splicing of MYO1B, CYT can inhibit the chemo-resistance of breast cancer." (PMID 40176901, 2025). "SRSF1 regulates the alternative splicing of MYO1B gene and inhibits its protein level, thereby inhibiting the proliferation, metastasis and stem cell properties of breast cancer cells, and promoting the chemosensitivity of drug-resistant breast cancer cells." (PMID 40176901, 2025). "SRSF1 promotes EMT, invasion and migration of breast cancer by generating the expression of splice variants lacking the BH3 structural domain." (PMID 36052258, 2022). "SRSF1 exerts oncogenic roles in breast cancer partially by regulating the alternative splicing of PTPMT1, which could be a therapeutic target candidate in breast cancer and a prognostic factor in HR + breast cancer patients." (PMID 36065311, 2022). "Cassette exons differentially spliced between high- and low-metastatic breast cancer cells showed enrichment for a number of RNA motifs, which could represent binding sites for RBPs involved in breast cancer malignancy, including PTBP1, SRSF1, and SRSF9." (PMID 33918758, 2021). "Indeed, several splice factors including BUD31, SF3B1 and SRSF1 are known to be gene targets of the oncoprotein MYC and inhibition or knockdown of those in MYC hyperactivated breast cancer cells impairs tumorigenesis." (PMID 31666932, 2019). "Among the SR proteins, SRSF1, SRSF2, SRSF3, SRSF5, and SRSF6 have been shown to be highly expressed in breast cancer." (PMID 31065692, 2019). "The SRSF1 gene is on a region of chromosome 17q23 which is amplified in some breast cancers, including in tumours with a poor prognostic outlook and in the MCF7 breast cancer cell line." (PMID 23935626, 2013). "Importantly, we found that several RBPs, which are able to recognize the enriched sequences at 5′ and 3′ splice-sites and inside the AS cassette exons, were differentially expressed in breast cancer and during breast tumor progression, including PTBP1, SRSF1, and SRSF9." (PMID 33918758, 2021). "To test whether SRSF1 could regulate the alternative splicing of CD44 in GC cells, as it was reported in breast cancer cells, we detected the relative levels of different CD44 isoforms in MGC-803 cells transfected with siRNA specific to SRSF1 or negative control." (PMID 31857793, 2019). "To find out whether other RBPs regulate translation initiation of specific mRNAs during tumor progression, we first analysed by immunohistochemistry (IHC) the expression of several RBPs (hnRNP A1, hnRNP H, RBM9/FOX2, SRSF1/ASF/SF2, SRSF2/SC35, SRSF3/SRp20, SRSF7/9G8) in breast cancers." (PMID 26930004, 2016).
lung carcinoma (46 papers, 2010 to 2026). "It has been shown that SRSF1 is associated with developmental disorders in lung cancer, and influences patients’ radioresistance." (PMID 38735973, 2024). "Collectively, we concluded that the oncogenic property of USP15 and USP4 is associated with SRSF1 that shows a parallel regulatory effect in lung cancer cell while the alternatively spliced isoform SRSF1-3 lacks such oncogenic functions." (PMID 35027535, 2022). "For example, siRNA-mediated knockdown of SRSF1 in this study prevented the inclusion of a lung carcinoma-associated exon in the transcript PRRC2C and significantly reduced cell growth." (PMID 25845590, 2015). "Hence, we sought to find the association of the two DUBs in the regulation of SRSF1 alternative splicing for lung cancer progression." (PMID 35027535, 2022). "In addition, the PI3K/Akt signaling pathway, constitutively activated by mutated EGFR, leads to SRSF1 hyper-phosphorylation and consequent reduction of the anti-apoptotic isoform Casp-9b in lung cancer." (PMID 32596243, 2020). "For example, Bcl-X can produce the anti-apoptotic long splicing isoform Bcl-XL, as well as the pro-apoptotic short isoform Bcl-XS, with RBM4 and SRSF1 modulating Bcl-X splicing, thereby influencing lung cancer development." (PMID 39897555, 2025). "Previous studies showed that parkin RBR E3 ubiquitin‐protein ligase (PARK2) and ring finger protein 125 (RNF125) can regulate Srsf1 ubiquitination in human lung cancer and liver cancer cells." (PMID 38520084, 2024). "For example, USP4 and USP15 promoted the growth of lung cancer cells via measuring selective splicing of SRSF1." (PMID 38581057, 2024). "hnRNP A1, for instance, is highly expressed in most cancers but seems to be a key proto-oncogene in particular in lung cancers where it antagonizes SRSF1 functions and deregulates the global RNA splicing environment." (PMID 35979354, 2022). "RBM4-S enhances lung cancer cell proliferation by antagonizing RBM4-FL-meditated tumor suppression through eliminating the inhibition effect of RBM4-FL on the SRSF1-mTORC1 signaling pathway." (PMID 35361747, 2022). "Collectively, our current study demonstrates USP15 and USP4 mediated lung cancer cell proliferation and migration by increasing the expression of functional full-length SRSF1 protein." (PMID 35027535, 2022). "In summary, we found that the deubiquitinating enzymes USP15 and its close paralog USP4 regulate alternative splicing of SRSF1 resulting in the isoform-specific functions in lung cancer cell." (PMID 35027535, 2022). "used genome-wide microarrays and an algorithm that uses data from exon and junction probes in order to identify a network of splicing events under control of SRSF1 in lung cancer." (PMID 35463320, 2022). "We found that SRSF1 is upregulated in several lung cancer cells compared to the normal lung epithelial cells, similar to the USP15 and USP4 expression patterns." (PMID 35027535, 2022). "Collectively, our current findings highlight the vital regulatory mechanism of SRSF1 alternative splicing in lung cancer cell, which strengthens the potentiality of SRSF1 as a diagnostic marker." (PMID 35027535, 2022). "Here, we found that USP15 and its close paralog USP4 are overexpressed and facilitate lung cancer cell proliferation by regulating the alternative splicing of SRSF1." (PMID 35027535, 2022). "Since both DUBs facilitate lung cancer cell proliferation and migration, and SRSF1 is a decisive candidate regulated by both DUBs, we subsequently tested SRSF1 endogenous expression to confirm its role in lung cancer progression as well." (PMID 35027535, 2022). "We observed an increased endogenous expression of SRSF1 in lung cancer cells as well, and its overexpression significantly enhanced cancer cell phenotype and rescued the depletion effect of USP15 and USP4." (PMID 35027535, 2022).
lung carcinoma (continued). "Our current study provides the first evidence of DUB-mediated regulation of SRSF1 alternative splicing that controls its oncogenic properties in lung cancer cell." (PMID 35027535, 2022). "Considering both DUBs are involved in the same cellular pathway and the imperative role of SRSF1 in lung cancer progression, we focused on SRSF1 hereafter." (PMID 35027535, 2022). "Here we found the enhanced oncogenic ability by SRSF1 in lung cancer cell, while the isoform SRSF1-3 was functionally inactive." (PMID 35027535, 2022). "In this study, we found that USP15 and USP4 regulate alternative splicing of SRSF1 resulting in the isoform-specific functions in lung cancer cell proliferation and migration." (PMID 35027535, 2022). "The SRSF1 gene was found overexpressed compared to matched normal tissue in approximately 20% of lung cancers." (PMID 34065983, 2021). "SFs, including QKI, RBM4, RBM5, RBM6, RBM10, and SRSF1, were involved in the development of lung cancer, as SFs play a regulatory role in splicing." (PMID 33047900, 2020). "Myc was also demonstrated to bind E-boxes in the SRSF1 promoter and to transactivate the SRSF1 overexpression that cause production of MKNK2 +13B and TEAD1 +5 isoforms and enhanced proliferation of lung cancer cells." (PMID 32596243, 2020). "A similar regulation was found for Casp-9 in lung cancer cells in which activated AKT phosphorylates SRSF1, thereby inhibiting synthesis of anti-apoptotic Casp-9b isoform." (PMID 29286307, 2017). "Depletion of SRSF1 in human A549 lung cancer cells reduces IFN-β through the expression of alternative IRF3 spliced variants, while SF3A1 silencing leads to a decreased induction of pro-inflammatory cytokines by promoting an alternative splice form of MyD88." (PMID 27454487, 2016). "More recently, SRSF1 overexpression was also reported in lung cancer and novel SRSF1 target transcripts were identified, including the genes, ATP11C, IQCB1, TUBD1, proline-rich coiled-coil 2C (PRRC2C), and survivin." (PMID 26273603, 2015). "CircCDR1as binds to SRSF1 and prevents its ubiquitination and degradation in lung cancer." (PMID 40356340, 2025). "In addition, the xenografts with parental HCC827 lung cancer cells developed the smallest tumors, whereas xenografts with SRSF1-knockdown Gefitinib-resistant cells developed smaller tumors as compared to controls, and grew much slower than controls as well." (PMID 33664238, 2021). "During radioactive tracer treatment of lung cancer cells, SRSF1 knockdown could sensitize cancer cells to irradiation via regulation of PTPMT1 splicing." (PMID 33996533, 2021). "Oncoprotein MYC could transcriptionally upregulate the expression of the SR protein splicing factor, SRSF1, in lung cancer cells, which triggered mRNA splicing of a series of kinases and facilitated oncogenic signaling." (PMID 35096927, 2021). "It has been reported that SRSF1 was able to regulate EMT through disrupting the alternative splicing of key tumor associated genes, including Ron proto-oncogene, PRRC2C, and MKNK2, to modulate lung cancer progression." (PMID 31832019, 2019). "Additionally, USP 15 and its homologue (USP 4) promote lung cancer cell proliferation by regulating SRSF1 alternative splicing, so targeting therapy against SRSF1 splicing factor may become a new strategy for SCLC treatment." (PMID 40129567, 2025). "In particular, SRSF1 has been described to interact with many different proteins to regulate several cellular functions, including splicing, and has been found overexpressed in several types of cancer (breast and lung cancer), where it is considered a proto-oncogene." (PMID 31561558, 2019). "Therefore, our data extend to lung carcinoma the aggressive property of SRSF1 protein." (PMID 23071587, 2012).
lung carcinoma (continued). "The HNRNPA2B1 levels were positively associated with TARDBP (R = 0.83), DHX9 (R = 0.73), HNRNPR (R = 0.77), SRSF1 (R = 0.79), HNRNPD (R = 0.75), and HNRNPM (R = 0.78) genes in lung cancer (all P < 0.001)." (PMID 35529270, 2022). "Previously, SRSF1 has been indicated to inhibit autophagosome formation by reducing the accumulation of LC3-II and numbers of autophagosomes in lung cancer cells by directly binding to PIK3C3." (PMID 35333349, 2022). "Reduced cytoplasmic availability of the Strubbelig-receptor family protein group (SRSF1, SRSF7, SRSF9) can determine autophagy suppression regulated by SRSF1 and apoptosis of colon and lung cancer cells induced by SRSF7 and SRSF9 reduction." (PMID 36066672, 2022). "As an example, SRSF1 (SF2/ASF) is particularly overexpressed in diverse human tumors such as breast or lung cancers." (PMID 35979354, 2022). "Reduced availability of the SRSF1 protein, which regulates autophagy activation, as well as SRSF7 and SRSF9, which induce apoptosis in colon and lung cancer cells by controlling apoptosis." (PMID 36066672, 2022). "Overexpression of several SR and SR-like proteins, in particular SRSF1, SRSF3, SRSF6 and TRA2β, was observed in lung cancer." (PMID 34065983, 2021). "In reports on radiotherapy for lung cancer, the binding site regulated by SRSF1 was TTACCAGTAA, and another report predicted and verified that the binding motif of SRSF1 derived from RNA-seq to regulate the AS of MYO1B is GAGGGG." (PMID 33992102, 2021). "Consistent with this possibility, Gefitinib-resistant HCC827 lung cancer cells, which had a much faster growth rate as compared to the parental HCC827 cells, also displayed elevated expression of SRSF1." (PMID 33664238, 2021). "Further validation revealed that knockdown of SRSF1 indeed increased the accumulation of LC3-II, but decreased the expression of P62 in A549 and H358 lung cancer cells." (PMID 33664238, 2021). "Similar splicing modulation was found for caspase-9 (Casp-9) in lung cancer cells, in which activated AKT phosphorylated SRSF1, thereby leading to exclusion of an exon 3,4,5,6 cassette and generation of the anti-apoptotic Casp-9b isoform." (PMID 29286307, 2017). "Overall, our results support the idea that variations in expression, localization and/or activity (through phosphorylation) of SRSF1 and SRSF2 proteins take place during lung cancer progression." (PMID 23071587, 2012). "In PM2.5-induced lung cancer, circCDR1as specifically binds to splicing factor 1 rich in serine/arginine (SRSF1), affecting SRSF1's splicing of VEGFA mRNA and ultimately inhibiting lung cancer cell apoptosis, thereby promoting the development of PM2.5-induced lung cancer." (PMID 40290118, 2025). "SRSF1 inhibited autophagy by adjusting Bcl-x splicing and combining PIK3C3 in lung cancer." (PMID 38581057, 2024). "We observed an increased expression of BIN1 through SRSF1 downregulation by USP15 and USP4 knockdown, which may, in turn, inhibits the metastatic ability of lung cancer cells." (PMID 35027535, 2022). "Some studies have reported SRSF1 and miR-9 involvement in EMT during lung cancer." (PMID 28806747, 2017). "Likewise, the colony formation and cell invasion ability of lung cancer cells were enhanced by the overexpression of SRSF1 but not by SRSF1-3." (PMID 35027535, 2022). "Thus, the enhanced cancer progression by SRSF1 but not by SRSF1-3 suggests that lung cancer cell progression is regulated by the alternative splicing of SRSF1." (PMID 35027535, 2022).